INS (insulin)
Diseases named in the same sentence as INS in open-access papers (continued):
Sharing a sentence is not in itself a finding about the gene and the disease.
Stroke (533 papers, 2001 to 2026). Sudden impairment of blood flow to a part of the brain due to occlusion or rupture of an artery to the brain. "Stroke can cause excessive secretion of catecholamines and insulin, which modulate the transmembrane transport of potassium via the Na+/K+-ATPase pump, leading to intracellular potassium influx and a subsequent decrease in serum potassium levels." (PMID 40308225, 2025). "Guidelines recommend energy restriction, physical activity, and behavioral therapy as first-line strategies because a 5–10% weight loss improves insulin sensitivity, blood pressure, and lipid profiles, lowering coronary and stroke risk." (PMID 41375653, 2025). "In a broader population, elevated TyG-BMI levels are associated with insulin IR-induced glucose metabolism disorders, lipotoxicity, and excessive inflammatory responses, thereby increasing the risk of stroke recurrence." (PMID 41561331, 2025). "Traditionally, BMI has been a key factor in assessing stroke risk, but our findings suggest that eGDR, as a marker of insulin sensitivity, should also be incorporated into routine health screenings." (PMID 40417114, 2025). "Real‐world data have found that in patients diagnosed with T2DM for less than 6 months, insulin therapy reduced the risk of stroke and hospitalization for heart failure." (PMID 41320960, 2025). "METS-IR demonstrates significant associations with pre-diabetes, DM, CVD, stroke, and hyperuricemia, outperforming other non-insulin-based IR surrogates in differential diagnosis." (PMID 41202057, 2025). "Linoleic and linolenic acid are both essential fatty acids that have been shown to have distinct health benefits, including lower cholesterol, improved insulin sensitivity, and lower risk of heart disease and stroke." (PMID 41007917, 2025). "Body mass index (BMI) and estimated glucose disposal rate (eGDR), indicators of adiposity and insulin sensitivity, respectively, are independently associated with stroke risk." (PMID 40417114, 2025). "Insulin resistance (IR), characterized by the body’s reduced response to insulin, has been identified as a contributor to stroke risk, primarily through its role in promoting atherosclerosis." (PMID 40134698, 2025). "Conversely, eGDR, a surrogate marker of insulin sensitivity, was negatively associated with stroke risk in our study, highlighting its protective role." (PMID 40417114, 2025). "It highlights that in multimorbid age-advanced population history of stroke, chronic heart failure and insulin therapy are linked to cognitive decline." (PMID 40818936, 2025). "Thiamine exerts a protective effect on the proliferation of human arterial smooth muscle cells mediated by glucose and insulin, which further prevents the occurrence of vascular atherosclerosis and reduces the risk of stroke." (PMID 40395549, 2025). "Perioperative haemodynamic fluctuations, surgical duration, and insulin management were also identified as key stroke risk factors." (PMID 40621196, 2025). "Insulin resistance (IR), defined as the need for higher doses of insulin to achieve a normal physiological response, has been linked to an increased risk of stroke through mechanisms such as atherosclerosis." (PMID 40417114, 2025). "Although its cardiovascular and stroke prevention benefits are proven, the potential fracture risks in at-risk populations, particularly stroke survivors and insulin-resistant individuals, necessitate careful consideration in individuals on pioglitazone." (PMID 40115256, 2025). "Epidemiological data have consistently demonstrated a close correlation between abnormal glucose and insulin levels and the risk of cardiovascular disease, such as heart attack, angina, heart failure, and stroke." (PMID 41450551, 2025). "Third, tea components can improve insulin sensitivity and lipid profiles, thereby indirectly reducing the risk of stroke in T2DM patients." (PMID 40537848, 2025).
Stroke (continued). "An increasing value of fasting insulin was associated with a reduction in the likelihood of exhibiting stroke." (PMID 39347227, 2024). "On the other hand, an increasing value of postprandial insulin and age was associated with an increased likelihood of exhibiting stroke." (PMID 39347227, 2024). "Our study identified age, fasting insulin, and postprandial insulin as key factors influencing stroke risk." (PMID 39347227, 2024). "We performed the OR analysis to measure the strength of association between the presence of HF, DPN, stroke, and insulin therapy and the likelihood of reduced quality of life (EQ-5D-3L < 50%)." (PMID 39124656, 2024). "These lifestyle changes can improve insulin sensitivity, reduce blood pressure, and ultimately lower the risk of stroke." (PMID 38812746, 2024). "In DM patients, systemic inflammation impairs insulin sensitivity, leading to poorly controlled blood sugar levels, significantly increasing the risk of stroke, diabetic nephropathy, and retinopathy." (PMID 39057115, 2024). "Higher fasting insulin levels were associated with a reduced risk of stroke, while increased postprandial insulin and age were linked to higher stroke risk." (PMID 39347227, 2024). "On the other hand, increasing insulin postprandial levels and age were associated with an increased risk of stroke." (PMID 39347227, 2024). "According to our predictive model, we found that an increase in fasting insulin levels was linked to a lower risk of stroke occurrence." (PMID 39347227, 2024). "Heart failure, stroke, insulin use, falls, and amputation were associated with greater odds of hospitalization over time." (PMID 39058533, 2024). "By leveraging a comprehensive dataset from East Coast Hospitals, Pondicherry, India, we aim to provide more definitive insights into how insulin levels impact stroke risk." (PMID 39347227, 2024). "On the other hand, increasing postprandial insulin levels and age were associated with an increased risk of stroke." (PMID 39347227, 2024). "A recent meta-analysis showed that patients who received insulin had a lower risk of stroke compared to those under sulphonylureas." (PMID 39407846, 2024). "This contrast permits us to be concerned with the chance of the association between stroke and insulin levels." (PMID 39347227, 2024). "In this cross-sectional study, we investigated the association between high insulin levels (both fasting and postprandial) and the occurrence of stroke within a dataset of 229 patients." (PMID 39347227, 2024). "Hyperinsulinemia, a condition marked by elevated insulin levels, has been associated with an increased risk of cardiovascular events, including stroke." (PMID 39347227, 2024). "The UKPDS study revealed a statistically insignificant association of basal insulin with stroke risk." (PMID 39407846, 2024). "There is evidence that weight loss, restoration of tissue sensitivity to insulin, and normalization of glucose homeostasis are very effective in stroke prevention." (PMID 36834685, 2023). "Age, sex, HR, severe stroke, smoking status, levels of total cholesterol, diastolic blood pressure, and the use of insulin after discharge were independently associated with glycemic control." (PMID 36991469, 2023). "Disability and reduced muscle function observed in stroke patients also contribute to the development of sarcopenia, which increases the risk of falls, insulin resistance, and mortality in the elderly." (PMID 35277045, 2022). "A database study from the UK showed that intensification of glucose-lowering therapy with GLP-1RA was associated with a 73% reduction in the risk of composite cardiovascular events, including stroke, compared to insulin." (PMID 35933524, 2022). "Combined exenatide and insulin treatment was associated with a similar lower HR for stroke (0.65; 95%CI 0.44–0.98) compared to insulin therapy alone in another database analysis." (PMID 35933524, 2022).
Stroke (continued). "Glycemic factors are clear and important interventional risk factors for stroke and prognosis, and it is critical to delve into the mechanisms by which high glycemic levels and insulin affect the benefits of thrombolytic nerve function." (PMID 36324389, 2022). "This is possibly due to the fact that anti-diabetic medications such as sulfonylurea and insulin can control hypercholesterolemia and, to some extent, reduce the risk of developing stroke." (PMID 35125102, 2022). "In the present observational study, insulin therapy showed an almost neutral effect on stroke risk in the final model." (PMID 35933524, 2022). "Limited data are available on stroke risk and other cardiovascular outcomes in various third-line glucose-lowering therapies, e.g. insulin and GLP-1RA." (PMID 35933524, 2022). "Secondly, previous research showed that insulin resistance affected platelet adhesion, activation and aggregation which were associated with artery stenosis or occlusion and involved in stroke occurrence." (PMID 33602208, 2021). "Patients with DM (especially insulin‐treated patients) had a significantly worse outcome for the composite endpoint and for all its components isolated (all‐cause mortality, MI, stroke, and unstable angina with urgent revascularization)." (PMID 33146924, 2020). "The results of the United Kingdom Prospective Diabetes Study (UKPDS) suggested that intensive blood glucose control with metformin, compared with the use of sulfonylureas or insulin, significantly reduced the risk of stroke." (PMID 31540142, 2019). "There seems, however, to be a significantly lower relative mortality risk among patients on insulin glulisine than on insulin aspart, as well as lower risk of stroke among users of glulisine in the total cohort and age 65 or older." (PMID 28702259, 2017). "Diminished insulin to IRS signalling has been implicated in the poor prognosis of diabetic patients following a stroke." (PMID 27514532, 2016). "Among those without history of renal and cardiovascular diseases, compared to the insulin group, patients in the EBID and EBID + insulin groups had a 63% (HR CI: 0.18, 0.75) and a 74% (HR CI: 0.16, 0.42) reduced risk of stroke, respectively." (PMID 25616979, 2015). "Patients in the EBID/EBID + insulin group had significantly reduced risk of HF, MI and stroke by 61/56%, 50/38% and 52/63% respectively, compared to patients in the insulin group (p < 0.01)." (PMID 25616979, 2015). "We did not investigate the endpoint stroke, because only two studies investigated the association between insulin and stroke." (PMID 23300589, 2012). "Few studies reported stroke endpoints and associations in women; as a consequence the pooled relative risk of stroke for insulin was based on two studies and the pooled relative risk for HOMA-IR was based on four studies." (PMID 23300589, 2012). "We used fixed and random-effect meta-analyses to calculate the pooled relative risk for CHD, stroke and combined cardiovascular disease, comparing high to low concentrations of glucose, insulin or HOMA-IR." (PMID 23300589, 2012). "There was weak statistical evidence that the association of fasting insulin with incident CHD or stroke was greater than the association of either fasting glucose or HbA1c with this outcome (both p = 0.09)." (PMID 17760500, 2007). "Our aim was to determine the independent associations of fasting insulin, glucose, and glycated haemoglobin with coronary heart disease and stroke in older women." (PMID 17760500, 2007). "For individuals with higher TyG-BMI, measures to improve insulin sensitivity, such as healthy eating, regular exercise, weight loss, and pharmacological interventions, may be key strategies to reduce stroke incidence." (PMID 40672456, 2025). "Conversely, receiving a T2DM or CHD diagnosis, especially in cases of stroke or the need for insulin injections, could cause psychological distress in patients." (PMID 40652160, 2025).
Stroke (continued). "Advanced age, history of stroke, heart failure and insulin treatment were associated with low MMSE." (PMID 40818936, 2025). "By improving insulin sensitivity, stabilizing glucose levels, optimizing lipid metabolism, and improving cerebrovascular function, MedDiet has been proven to reduce the risk of stroke, MCI, and AD in T2DM patients." (PMID 40896190, 2025). "Our results support the use of eGDR as a valuable marker for identifying individuals who may benefit from interventions aimed at improving insulin sensitivity and reducing stroke risk." (PMID 40134698, 2025). "It has also been suggested that elevated insulin levels induce pro-inflammatory responses, which may increase the risk of stroke." (PMID 39407846, 2024). "Second, our results suggest that interventions aimed at improving insulin sensitivity and glycemic control could potentially mitigate the risk of stroke in individuals with high RC levels." (PMID 39713218, 2024). "An increase in fasting insulin levels was linked to a lower risk of stroke occurrence." (PMID 39347227, 2024). "The variables most associated with stroke seem to be age, insulin fasting, and postprandial." (PMID 39347227, 2024). "Additionally, in a population-based case control study, patients who received combined therapy with insulin and metformin had a similar risk of stroke (OR, 0.98; 95% CI, 0.63–1.52) to those who treated with metformin in combination with a sulphonylurea." (PMID 39407846, 2024). "Hence, future research projects covering a larger sample size focusing on fasting insulin and its association with stroke risk should be implemented to address the scarcity of evidence available." (PMID 39347227, 2024). "In addition, the ELiR intervention focuses on total PA throughout the day, which was reported to be associated with glucose and insulin sensitivity in stroke survivors." (PMID 36860816, 2023). "Therefore, the association between adipose tissue specific insulin resistance and stroke prognosis is still unclear." (PMID 38041145, 2023). "For example, one study found that substituting common refined carbohydrates such as white rice with pasta, which has a lower glycemic index and hence produces a lower post-prandial insulin spike, was associated with a lower risk of stroke and atherosclerotic cardiovascular diseases." (PMID 37242214, 2023). "Insulin is associated with weight gain, which may indirectly increase stroke risk, whereas adding GLP-1RA has favorable effects on weight reduction." (PMID 35933524, 2022). "Insulin is important for maintaining the functional integrity of the brain, and peripheral and central insulin dysfunction due to IR may be an independent risk factor for stroke." (PMID 36589857, 2022). "Insulin treatment has also been associated with increased stroke risk and higher mortality." (PMID 33478504, 2021). "The association between insulin sensitizers and stroke has been observed previously." (PMID 32733045, 2020). "In the Uppsala Longitudinal Study of Adult Men who were free from stroke at age 70 years and followed for approximately 9 years, a one standard deviation increase in insulin sensitivity measured by a euglycemic clamp decreased the risk for subsequent stroke or transient ischemic attack (TIA)." (PMID 33375333, 2020). "Insulin sensitizers and incretins were associated with lower stroke risk." (PMID 32733045, 2020). "In the subgroup analyses, subjects in GGT ASV quartile 4 consistently had an increased risk for all-cause mortality and stroke during follow up, with the exception of those with a history of insulin treatment or 4–6 classes of oral antidiabetic drugs in the stroke analysis." (PMID 32958798, 2020). "The need for insulin might be associated with more than a sevenfold increased risk of perioperative stroke and death after CEA." (PMID 30909911, 2019).
Stroke (continued). "Compared with Q1 and after adjusting for age, gender, race, hemoglobin, SBP, smoking, cholesterol, and insulin use, patients in Q4 had higher risk of MI (OR 3.17 [2.17–4.64], P < 0.001), stroke (OR 1.12 [1.03–1.22], P = 0.006), and CKD (OR 1.13 [1.05–1.21], P = 0.002)." (PMID 29359154, 2017). "Also, DPP4i users had a significantly lower stroke risk than that of meglitinides and insulin users, but higher than that of pioglitazone users." (PMID 26932742, 2016). "A positive association between MetS and atherothrombotic stroke has been reported, and the etiopathological mechanisms of atherothrombosis (e.g., via vasomotor reactivity impairment, insulin resistance, inflammation, oxidative stress, platelet activation and hypercoagulation) have been proposed." (PMID 26269150, 2015). "“I agreed to take insulin after the doctor informed me that high blood sugar could cause stroke and kidney failure." (PMID 24164794, 2013). "These micronutrients may mediate beneficial effects on several risk factors for stroke, e.g. blood pressure, insulin resistance, platelet aggregation and atherosclerotic processes." (PMID 19457271, 2009). "Cold temperatures may influence cardiovascular mechanics through increased blood viscosity, platelet aggregation, metabolic derangements, insulin resistance, and changes in red blood cell count, all of which increase the risk of ischemic heart disease and stroke." (PMID 40125174, 2025). "Fasting insulin level has been debated for a reliable IR parameter, for example, fasting insulin could not predict the risk of cardiovascular disease, such as coronary heart disease and stroke." (PMID 36568072, 2022). "Inactivity and immobilization after stroke are important factors of muscle loss or decreased fiber cross-sectional area as muscle unloading produces a multitude of maladaptive responses, such as insulin resistance, glucose-dependent energy metabolism, and intramuscular lipid disposition." (PMID 34845407, 2021). "Conversely, male subjects with a previous stroke and insulin usage presented significantly lower MMSE scores." (PMID 40818936, 2025). "In the training set, we used the LASSO regression model to identify nine factors with non-zero coefficients, including age, marital status, PIR, CHF, CHD, stroke, taking insulin, red blood cell count, and creatinine levels." (PMID 40060382, 2025). "Among diabetic patients, those with suboptimal insulin use or poor glycemic control have a significantly higher likelihood of postoperative stroke compared to those with good glycemic control." (PMID 40621196, 2025). "Studies have shown that individual differences in spontaneous pain intensity in post-stroke CRPS are influenced by how insulin affects the resting-state functional connectivity (rsFC) of the prefrontal cortex." (PMID 40400911, 2025). "The model included seven predictors: age, marital status, CHF, CHD, stroke, creatinine level, and taking insulin." (PMID 40060382, 2025). "Aging is also associated with changes in certain metabolic parameters, such as blood glucose levels, insulin sensitivity, and lipid signaling and storage, which can also affect the pathological progression of stroke." (PMID 40867143, 2025). "The European Stroke Organization recommends controlling serum glucose through intravenous insulin infusion in a manner that mimics normal physiology while avoiding boluses with high-dose subcutaneous insulin." (PMID 39982264, 2025). "Furthermore, inflammatory markers partially mediated the association between eGDR and stroke, suggesting that low‐grade inflammation may represent a potential underlying mechanism through which impaired insulin sensitivity and resistance contribute to stroke occurrence." (PMID 40474525, 2025). "In summary, considerations are presented regarding the metabolic alteration involving triglycerides, insulin resistance, central obesity resulting in thromboembolism, arrhythmia, heart failure, stroke and coronary disease." (PMID 40989546, 2025).